SLC33A1 (solute carrier family 33 member 1)
Description:
Acetyl-CoA transporter that mediates active acetyl-CoA import through the endoplasmic reticulum (ER) membrane into the ER lumen where specific ER-based acetyl-CoA:lysine acetyltransferases are responsible for the acetylation of ER-based protein substrates, such as BACE1. Necessary for O-acetylation of gangliosides.
Synonyms: AT-1; ACATN; AT1; CCHLND; HPBDS; SPG42
Tractability: Antibody: its Gene Ontology location is reachable by antibodies, with high confidence; UniProt predicts a signal peptide or a membrane-spanning region. PROTAC: ubiquitination databases record sites on it; its protein half-life has been measured; a small molecule that binds it is known.
Target class: SLC33 acetylCoA transporter; Transporter; Electrochemical transporter; SLC superfamily of solute carriers
Gene: Protein-coding gene on chromosome 3 (155,821,024 to 155,854,456, reverse strand). Ensembl gene ENSG00000169359.
Subcellular location: Endoplasmic reticulum membrane
Subcellular location (Human Protein Atlas): Cytosol; Vesicles
Pathways (Reactome):
Disease: Defective SLC33A1 causes spastic paraplegia 42 (SPG42)
Transport of small molecules: Transport of vitamins, nucleosides, and related molecules
Gene Ontology:
Molecular function: acetyl-CoA transmembrane transporter activity; protein binding; protein homodimerization activity
Biological process: acetyl-CoA transmembrane transport; transmembrane transport
Cellular component: endoplasmic reticulum membrane; membrane; Golgi membrane; plasma membrane
Genetic constraint (gnomAD): Loss-of-function variants: 9 observed, 28.3 expected, observed/expected ratio (o/e) 0.32, 90% interval 0.19 to 0.56. The upper end of that interval is the gene's LOEUF score, 0.56, which puts it in group 2 of 6, group 1 being the genes least tolerant of losing a copy. Missense variants: 357 observed, 492.37 expected, observed/expected ratio (o/e) 0.73, 90% interval 0.66 to 0.79. Synonymous variants: 195 observed, 190.33 expected, observed/expected ratio (o/e) 1.02, 90% interval 0.91 to 1.15.
Homologues: Orthologues: chimpanzee SLC33A1 (99% identical), macaque SLC33A1 (99% identical), mouse Slc33a1 (94% identical), rat Slc33a1 (93% identical), guinea pig SLC33A1 (93% identical), dog SLC33A1 (91% identical), rabbit SLC33A1 (87% identical), pig SLC33A1 (86% identical), tropical clawed frog slc33a1 (71% identical), zebrafish slc33a1 (69% identical), Drosophila melanogaster CG9706 (49% identical), Caenorhabditis elegans T26C5.3 (49% identical). Paralogues in human: SLC33A2 (18% identical).
Diseases named in the same sentence as SLC33A1 in open-access papers:
SLC33A1 is named in the same sentence as 33 diseases in open-access papers, as found by Europe PMC text mining. Sharing a sentence is not in itself a finding about the gene and the disease. The quoted sentences say what the papers report.
developmental delay (4 papers, 2018 to 2021). "Mutations and duplication events in AT‐1/SLC33A1 are highly pleiotropic and have been linked to diseases such as spastic paraplegia, developmental delay, autism spectrum disorder, intellectual disability, propensity to seizures, and dysmorphism." (PMID 30051577, 2018).
Huppke-Brendel syndrome (3 papers, 2020 to 2025). "Another disease leading to the disorder of Cu metabolism is Huppke-Brendel syndrome, resulting from the mutation of the SLC33A1 gene encoding the AT-1 protein, first described in 2012." (PMID 32806787, 2020).
Spastic paraplegia (3 papers, 2015 to 2019). Complete loss of the ability to move the lower limbs accompanied by spasticity of the lower limbs. "Heterozygous mutations in SLC33A1 have been associated with spastic paraplegia (SPG42) with ataxia in a single family, and likewise, missense mutations in PLEKHG4 have been implicated in dominant late onset forms of spinocerebellar ataxia in Japanese individuals." (PMID 25976027, 2015). "A loss‐of‐function mutation in ACATN1/SLC33A1 has been associated with spastic paraplegia (SPG42,), although this observation could not be replicated in a subsequent study." (PMID 29055035, 2017).
autism spectrum disorder (2 papers, 2023 to 2025). A spectrum of developmental disorders that includes autism, and Asperger syndrome. "Gene duplication events involving 3q25.31 (harboring AT-1/SLC33A1) and 2p13.1 (harboring ATase1/NAT8B and ATase2/NAT8) are associated with autism spectrum disorder with intellectual disability and progeria-like dysmorphism." (PMID 40930841, 2025).
lung adenocarcinoma (2 papers, 2025 to 2026). A carcinoma that arises from the lung and is characterized by the presence of malignant glandular epithelial cells. "Consistent with this function, we find that pharmacologic inhibition of SLC33A1 with IXA4 selectively reduces viability of KEAP1-deficient lung adenocarcinoma cells that have elevated levels of glutathione, mimicking the sensitivity of these cells to genetic deletion of SLC33A1." (PMID 41757008, 2026).
hereditary spastic paraplegia (1 paper, 2017). Hereditary spastic paraplegias (HSP) comprise a genetically and clinically heterogeneous group of neurodegenerative disorders characterized by progressive spasticity and hyperreflexia of the lower limbs. "Homozygous Slc33a1S113R mutant mice were embryonic lethal, whereas heterozygous Slc33a1 mutant mice (Slc33a1wt/mut) exhibited behavioral abnormalities and central neurodegeneration, which is consistent with hereditary spastic paraplegia (HSP) phenotypes." (PMID 27935820, 2017).
hereditary spastic paraplegia type 42 (1 paper, 2017). "The S113R mutation (c.339T>G) (MIM #603690.0001) in SLC33A1 (MIM #603690), an ER membrane acetyl-CoA transporter, has been previously identified in individuals with hereditary spastic paraplegia type 42 (SPG42; MIM #612539)." (PMID 27935820, 2017).
laryngeal carcinoma (1 paper, 2019). Carcinoma that arises from the laryngeal epithelium. "The prognosis of laryngeal cancers could be improved by addition of markers such as IL1RAP, LANCL2, RYK, and SLC33A1." (PMID 31310629, 2019).
lung carcinoma (1 paper, 2026). "The endoplasmic reticulum (ER) transporter solute carrier family 33 member 1 (SLC33A1) has emerged as an attractive therapeutic target in etiologically diverse diseases, ranging from lung cancer to neurodegenerative disorders." (PMID 41757008, 2026).
muscular atrophy (1 paper, 2022). The loss of muscle tissue due to inactivity or disease. "Race-related heterozygous mutation in the Solute Carrier Family 33 Member 1 (SPG42/SLC33A1) in Chinese lineages with haploinsufficiency at 3q25.31 shows classical signs of hyperreflexia, lower extremity muscular atrophy, and pes cavus at varying ages from 4 to 42 but predominately around 20 years." (PMID 35163618, 2022).
Turner syndrome (1 paper, 2017). Turner syndrome is a chromosomal disorder associated with the complete or partial absence of an X chromosome. "Eight TFs and four ERFs are among the differentially expressed genes, as well as eight genes associated with Turner syndrome (PROCR, NR3C1, INSR, APOB, BMP15, F8, IL6, and WAS) and two genes that are haploinsufficient in humans (RAD50 and SLC33A1)." (PMID 28818098, 2017).
cancer (2 papers, 2023 to 2025). A tumor composed of atypical neoplastic, often pleomorphic cells that invade other tissues. "Interestingly, most of these genes are linked with cancer processes (Pld1, Fam13c, Svbp, TMem192, Zc3h7a, RTP4, Naa30, Zgrf1, Slc33a1, Dnmt3b, Map6, Plin4, Eps8L2, Alg12, Capg and Tdp2)." (PMID 37700325, 2023).
SLC33A1 also shares sentences with these, for which no sentence is quoted: Intellectual disability (3 papers); congenital cataracts (2); progeria (2); Ataxia (1); autosomal dominant spastic paraplegia (1); Autosomal dominant spastic paraplegia type 42 (1); cerebral palsy (1); copper metabolism disorders (1); epilepsy (1); Epileptic encephalopathy (1); Granuloma (1); Hypoglycemia (1); infection (1); Langer mesomelic dysplasia syndrome (1); MEDNIK syndrome (1); neurodegenerative disease (1); neurodevelopmental disorder (1); pericardial effusion (1); spinocerebellar ataxia (1); viral infection (1); Wilson disease (1).